IL17A (interleukin 17A)
Diseases named in the same sentence as IL17A in open-access papers (continued):
Sharing a sentence is not in itself a finding about the gene and the disease.
Allergy (139 papers, 2008 to 2026). An allergy is an immune response or reaction to substances that are usually not harmful. "By contrast, OVA allergy Tomato+ cells upregulated Th17-associated genes (Il17a, Il22, Rorc, Them176a)." (PMID 37191720, 2023). "IL-17A–producing γδ T cells within the lung consist mostly of Vγ4+ and Vγ6+ cells that can function as either protective or pathogenic cells during infection, inflammation, and allergy." (PMID 36480166, 2023). "In vivo results were further supported by proliferation and activation of IL6 and IL17A secretion in splenocytes treated with rAni s 1 or rAni s 9, suggesting that IL17 might play a critical role in the Anisakis-associated allergic reaction." (PMID 30245697, 2018). "Accordingly, in our in vitro model we clearly identified that the stimulation with rhIL-17A promotes the release of IL-8 in both nasal and bronchial epithelial cells suggesting that IL-17A might cause the IL-8 mediated airway inflammation in the allergic disease of the nose and of the bronchi." (PMID 23573194, 2013). "The results showed that Lp synergistic FOS significantly decreased clinical allergy scores, inhibited specific antibodies (IgE, IgG, and IgG1), IL-4, IL-6, and IL-17A levels, and increased IFN-γ and IL-10 levels." (PMID 39796399, 2025). "In a mouse model of allergies, L. acidophilus had a mitigating effect on blood levels of IL‐6 and IL‐17, as well as a downregulating impact on the expression of IL‐17A and retinoic acid‐related orphan receptor (ROR)‐γt (RORγt) in the spleen." (PMID 37904683, 2023). "The general linear model showed a significant main effect of group (allergy vs. healthy) on the levels of IL-17A and IFN-γ." (PMID 38090557, 2023). "Another study showed that IL-17A tested in BALF was associated with pulmonary pathogenesis during RSV infection and exacerbation of allergic disease in a mouse model." (PMID 36793128, 2023). "IL17A plays a vital role in the occurrence and development of allergic diseases, particularly, AD, AR, and AA." (PMID 35678682, 2022). "IL-17E is also known as IL-25, and because it presents low homology with other molecules of the family and contributes to the induction of allergies, it is thought to have functions different from those of IL-17A." (PMID 28316374, 2017). "We identified that microbiota associated with allergy later in childhood induced increased CD4+ T-cell RORγt expression, and elevated production of IL-17A and IgA, both at local intestinal and systemic sites, indicating expanded Th17 responses." (PMID 29250074, 2017). "This is evident in the accumulation of neutrophils in allergic diseases with high IL-17A and IL-17F production." (PMID 29311948, 2017). "IL-4, IL-13, eotaxin, and CysLT play very important roles in allergy, and their concordant actions in bone-marrow suggest that IL-17A effects on bone-marrow are generally attenuated by mediators of allergy, in a way consistent with in vivo observations." (PMID 26199466, 2015). "By contrast, less is known about IL-17A effects on eosinophils, which are closely related to neutrophils but remain better known for their pathogenetic roles in allergy than for their contributions to antimicrobial defences." (PMID 26199466, 2015). "To address this we analyzed the percentage of CD177+ IL-17A+ neutrophils from asthmatic patients that are allergic to specific groups of allergens based on positive intradermal allergy test reactions." (PMID 23822853, 2013). "Notably, VYC‐15 L led to increased IL17a production from γδ+ T cells and elevated systemic IgE levels, suggesting a potential link to delayed‐type hypersensitivity or allergy‐like responses." (PMID 40635637, 2025). "This study attributes to IL-17 a pro-inflammatory role in allergy of the airways." (PMID 37445595, 2023). "However, to date, most studies on the role of IL-17A in the pathogenesis of allergic diseases have been carried out using animal models, so it is difficult to apply the obtained conclusions to humans." (PMID 35805534, 2022).
Allergy (continued). "Some studies, however, haveprovidedconflictiongdata for the role of IL-17A_ rs8193036 in allergy." (PMID 26196693, 2015). "Nevertheless, the relationship between IL-17A and the cytokine environment of allergy is complex." (PMID 26199466, 2015). "Th17 cells and IL-17A play a role in the development and progression of allergic diseases." (PMID 23573194, 2013). "Moreover, IL-17A reduction and attenuated food allergen-responsive Th17 cells in IgE-mediated food allergy patients suggest a protective correlation between Th17 augmentation and allergy prevention." (PMID 40509380, 2025). "IL‐17A (IL‐17) is mainly produced by Th17 cells and belongs to the IL‐17 family of cytokines, IL‐17A to F. While IL‐17 plays a major role in inflammatory and autoimmune disorders, more data was published in recent years elucidating the role of IL‐17 in allergic diseases." (PMID 34429872, 2021). "However, IL-17F and IL-17A have overlapping yet distinct proinflammatory roles in host immune and defense mechanisms, such as mucoepithelial bacterial infections, inflammatory responses, and allergic diseases." (PMID 26146463, 2015). "During the effector phase of allergic response, NK cell depletion increased the number of OVA-specific CD4+ T cells and the levels of IL-23, IL-17A, and IFN-γ." (PMID 37448795, 2023). "IL-17A and IFN-γ can act on many cytokines and play an important role in the occurrence and development of allergic diseases." (PMID 38090557, 2023). "L. acidophilus reduced the serum IL-6 and IL-17 levels and downregulated IL-17A expression, but upregulated CD25, Foxp3, and TGF-β expression in a murine model of allergy." (PMID 35216600, 2022). "A subpopulation identified as Th cells (sTh#1) was significantly differing between allergy groups and the control group in the co-expression of TNF-α and IL-17A." (PMID 32698761, 2020). "It is found that exogenous LL-37 decreased TNF and IL17A expression while inducing anti-inflammatory IL-10 and TGF-β production in dendritic cells in allergy and inhibit LMW-hyaluronan-induced cytokine release in skin fibroblast." (PMID 31260471, 2019). "In previous allergy models of Anisakis infection in C57BL/6 mice, significantly increased Th17-related cytokines IL6 and IL17A were observed after subchronic treatment (7 times over 15 days) with recombinant Ani s 1 (rAni s 1) allergen." (PMID 30245697, 2018). "Although IL-17A-heterozygous (Il17a+/−) mice show half–levels of IL-17A production compared with wild-type mice, the development of certain allergic diseases, including CHS, in Il17a+/− mice was similar to in wild-type mice." (PMID 30356086, 2018). "The Th1/Th2 paradigm in adult allergic disease seems not to be applied in infants, where a stronger Th1 and Th2 bias has been demonstrated, with deficient production of IFN‐γ, IL‐4, and IL‐17A." (PMID 40952045, 2026). "Therefore, it is necessary to increase the sample size to explore the relationship between other types of allergies and IFN-γ and IL-17A levels in saliva." (PMID 38090557, 2023). "These two important cytokines IL-17A and IFN-γ, also play important roles in allergic diseases." (PMID 38090557, 2023). "Furthermore, the IL-17A, IL-23, IFN-, IL-4, and IL-10 serum levels were also compared according to gender, antihistamine receiving, nose picking, bleeding of the gums, smoking, familial history of epistaxis, and clinical presentations similar to allergies." (PMID 35145935, 2022). "Also, the serum levels of the TH17 cytokine IL-17A were slightly, but not significantly, elevated in the allergy model." (PMID 27445696, 2016).
gastric cancer (139 papers, 2010 to 2026). A primary or metastatic malignant neoplasm involving the stomach. "Gastric cancer, the fifth most frequent cancer worldwide and the fifth major cause of cancer-related fatalities has minimal study on IL-17A, and its function in gastric cancer development and therapy remains contentious." (PMID 39676857, 2024). "Specifically, the release of IL-17A by diverse immune cells has been associated with both tumor development and inhibition in gastric cancer." (PMID 39676857, 2024). "As a result, Th17 and IL-17A were positively linked to cognitive impairment in elderly gastric cancer patients." (PMID 36386524, 2022). "The polymorphisms of IL-17A G197A (rs2275913) and IL-17F A7488G (rs763780) has been associated with susceptibility to various types of proinflammatory diseases and gastric cancer." (PMID 32616024, 2020). "A previous study reported that IL-17A and IL-17F single nucleotide polymorphisms (SNPs) are associated with the risk of developing gastric cancer." (PMID 25663919, 2015). "A 1:1 matched case-control study was conducted to analyze the association between three common interleukin (IL)-17A and IL-17F single nucleotide polymorphisms (SNPs) and the risk of developing gastric cancer." (PMID 25663919, 2015). "In all selected publications, seven studies focused on gastric cancer and the results also indicated that IL-17A rs2275913G>A polymorphism plays an important role during the development of gastric cancer." (PMID 25147431, 2014). "Polymorphisms in IL-17A (rs2275913) and IL-17F (rs763780) have recently been identified to be associated with the susceptibility to rheumatoid arthritis, gastric cancer and ulcerative colitis, respectively." (PMID 22461912, 2012). "The results of a meta-analysis covering 10 case-control studies, involving 4516 cases and 5645 controls, showed a significant association between IL-17A polymorphisms and the risk of developing cancer, particularly gastric cancer, in the Asian (and Chinese) population." (PMID 35012470, 2022). "IL-17 may be negatively associated with gastric cancer as mice with IL17A developed less severe gastric inflammation." (PMID 35892729, 2022). "Also, IL-17A and IL-17F were investigated in gastric cancer risks and the association of each single nucleotide polymorphism (SNP) with subtypes of gastric cancer according to its clinicopathological features and their roles in prognosis." (PMID 32616024, 2020). "Therefore, the present study conducted a case-control investigation to provide a more reliable conclusion of the association between the IL-17A and IL-17F SNPs, and gastric cancer." (PMID 25663919, 2015). "However, subsequent replication studies investigating the association between IL-17A and IL-17F variants with the risk of developing gastric cancer were controversial." (PMID 25663919, 2015). "The succeeding stratified analysis according to HWE, ethnicity, and study design subgroup also presented that the IL-17A rs2275913G>A polymorphism may be a strong risk factor in the development of cancer, especially gastric cancer, in the Chinese population." (PMID 25147431, 2014). "In gastric cancer, it can lead to tumor progression by promoting T-helper cell subsets that produce tumor-promoting interleukin 17A through a series of pathways." (PMID 40313883, 2025). "For example, Streptococcus anginosus activates the Nrf2–HO‐1/NQO‐1 pathway, elevating ROS levels and consequently reducing the infiltration of CD8+IL‐17A+ Trm cells and lowering IL‐17A expression, thus promoting gastric cancer progression." (PMID 41028942, 2025). "Gastric cancer tissues exhibiting elevated levels of IL-17AmRNA and IL-17A contained a greater abundance of anti-tumor mast cells and NK cells, and lower tumor-promoting macrophages, the mechanisms involved require further study." (PMID 39814702, 2025).
gastric cancer (continued). "IL-17RC is upregulated in helicobacter pylori-induced gastric cancer tissues and human cancer tissues, participating in the IL-17A/IL-17RC axis and modulating the development of GC through the NF-κB/NOX1 signaling pathway." (PMID 39906741, 2024). "Previous investigations emphasized the discovery of IL-17 in patients with gastric cancer, although the involvement of IL-17A-positive cells in the cancer microenvironment has not been concluded." (PMID 39676857, 2024). "assessed two distinct gastric cancer cohorts, The Cancer Genome Atlas cohort and Zhongshan Hospital cohort, and proposed that the primary IL-17A+ cells in the TME of gastric cancer are likely Th17 cells, which play a role in delaying tumor progression." (PMID 39676857, 2024). "It has been noticed that tumor‐linked neutrophils can produce IL‐17A, promoting epithelial‐mesenchymal transition (EMT) in gastric cancer via JAK2/STAT3 signaling cascade." (PMID 36480232, 2023). "Increased expression of pro‐inflammatory cytokines and chemokines such as IL‐17A, IL‐22, and IL‐1 family members IL‐1β is involved in gastric cancer progression." (PMID 37306187, 2023). "IL-17a secretion by CAFs markedly enhances tumorigenic effects of gastric cancer through the JAK2/STAT3 pathway in the gastric cancer cells in vitro, with CAFs acting as an independent risk factor for DFS and DSS." (PMID 37046676, 2023). "TANs-derived IL-17a promotes EMT of gastric cancer cells, and blockade of IL-17a signaling inhibits TANs-induced phenotypes in gastric cancer cells." (PMID 37056931, 2023). "Our findings indicate that IL-17A promotes gastric cancer growth, oxidative stress, and CSC stemness by regulating the IL-17RC/NF-κB/NOX1 pathway." (PMID 36125689, 2023). "Stimulation of gastric cancer cells with recombinant human IL-17A protein promotes cell growth, ROS generation and increased stemness of tumor stem cells." (PMID 37978543, 2023). "On the basis of the results obtained so far, we suggest that serum determination of interleukin-17A would be helpful in the clinical practice of managing Helicobacter pylori-infected patients, and eventually for predicting the development of gastric cancer." (PMID 36980548, 2023). "More than 70% of the IL-17A in the disseminated peritoneal tissues of gastric cancer was present in the mast cells, and the number of cells with double-positive immunostaining (IL-17A and mast cells) was positively correlated with peritoneal fibrosis." (PMID 35740521, 2022). "Activation of STAT3 by IL-17A impacts quiescent gastric cancer stem cells (CSCs), which showed EMT-like transformation after exposure to IL-17A." (PMID 34944729, 2021). "In conclusion, the major source of IL-17A is mast cells, and IL-17A contributes to tumor progression and fibrosis in the peritoneal dissemination of gastric cancer." (PMID 32488650, 2021). "IL-17A derived from mast cells contributes to tumor fibrosis in peritoneal dissemination of gastric cancer." (PMID 32488650, 2021). "In the present study, we showed that mast cells are the major source of IL-17A in peritoneal dissemination of gastric cancer." (PMID 32488650, 2021). "A major source of IL-17A in the primary lesions of gastric cancer is mast cells, and the amount of IL-17A secreted by mast cells is correlated with poor overall survival." (PMID 32488650, 2021). "In this study, we examined which cells are the major source of IL-17A and the relationship between tissue fibrosis and IL-17A in peritoneal dissemination of gastric cancer." (PMID 32488650, 2021). "Some studies reported that the IL-17A pathway in lung adenocarcinoma and gastric cancer cells induces EMT via STAT3." (PMID 32488650, 2021). "Recently, the prognostic value of IL-17 mRNA and IL-17A+ cells has been studied in two independent large cohorts of Chinese gastric cancer patients." (PMID 31035644, 2019).
gastric cancer (continued). "The IL-17A level in MDDCs of healthy individuals and gastric cancer patients challenged with H. pylori was significantly higher than in MDDCs which were not pulsed with H. pylori." (PMID 22526791, 2012). "The results showed that as compared with healthy individuals, the maturation marker CD40 in MDDCs, IL-17A expression from T cells, and IL-10 expression from MDDCs were significantly lower in gastric cancer patients." (PMID 22526791, 2012). "Subsequently, we demonstrated through CCK-8 assays, scratch wound healing assays, and Transwell invasion assays that both IL-17A and IL-26 significantly enhanced the proliferation, migration, and invasive capacities of gastric cancer cells, thereby facilitating gastric cancer progression." (PMID 40452847, 2025). "Interestingly, Gastric cancer cells can stimulate mast cells to secrete IL-17A through degranulation of the PI3K-AKT pathway by secreting adrenomedullin (ADM), hence facilitating tumor growth." (PMID 39814702, 2025). "Tc17 cells, neutrophils, and gastric cancer-derived IL-17A all exhibited tumor-promoting effects." (PMID 39676857, 2024). "Based on the current study, it can be concluded that whether IL-17A is good or bad in gastric cancer depends on the stage at which it is present and its cellular origin." (PMID 39676857, 2024). "Additionally, the same study reported that higher IL-17A expression was observed in the tumors from patients with advanced gastric cancer compared with early cancer." (PMID 38639570, 2024). "TANs activate the JAK2/STAT3 pathway in gastric cancer cells by secreting interleukin-17a (IL-17a)." (PMID 39050856, 2024). "Inhibition of IL-17a reverses the protumorigenic effects of CAFs in vitro in gastric cancer." (PMID 37046676, 2023). "Indeed, high levels of IL-17A have been shown to be independent predictors of poor survival in gastric cancer patients." (PMID 37609436, 2023). "We suggest that measurement of serum IL-17A might be useful for the management of Helicobacter pylori-infected patients, and eventually for predicting the development of gastric cancer." (PMID 36980548, 2023). "Moreover, the IL-17A released by mast cells was found to promote the peritoneal dissemination of gastric cancer by inducing the occurrence of MMT in PMCs in nude mice." (PMID 35740521, 2022). "In gastric cancer, TANs promoted the migration and invasion of tumor cells by secreting IL-17a." (PMID 35118116, 2021). "Indeed, in gastric cancer higher IL-17A expression was also found in more aggressive and larger tumours." (PMID 31295246, 2019). "Finally, it has been reported that activated mast cells release IL-17A which promoted the in vitro proliferation of gastric cancer cells." (PMID 31035644, 2019). "Various studies have demonstrated that IL-17A and IL-17F may be involved in the development of gastric cancer, however, the results were unclear." (PMID 25663919, 2015). "Moreover, in gastric cancer tissues, RORγ was upregulated 2–54 fold compared to matched normal samples in 23 of 24 samples examined, and IL-17A mRNA was increased 2–30 fold." (PMID 23365642, 2013). "Thus, we examined the presence of the Th17 using RORγ and IL-17A markers in mucosa derived from normal samples, H. pylori infected samples with gastritis, and matched normal and gastric cancer tissues from the same patient." (PMID 23365642, 2013). "However, IL-17A production was significantly lower in MDDCs from gastric cancer patients than from healthy individuals." (PMID 22526791, 2012). "Accumulating evidence implicates IL-17A and Th17 responses in the pathogenesis of gastric cancer." (PMID 22761739, 2012). "Elevated levels of IL-17A have been detected in patients with autoimmune gastritis, gastrointestinal metaplasia, and atypical hyperplasia, indicating that a protracted Th17 response may occur before the development of gastric cancer." (PMID 39676857, 2024).